SPTA1 (spectrin alpha, erythrocytic 1)
Description:
Spectrin is the major constituent of the cytoskeletal network underlying the erythrocyte plasma membrane. It associates with band 4.1 and actin to form the cytoskeletal superstructure of the erythrocyte plasma membrane.
Synonyms: SPTA; EL2; HPP; HS3; SPH3
Tractability: Antibody: its Gene Ontology location is reachable by antibodies, with medium confidence. PROTAC: ubiquitination databases record sites on it.
Gene: Protein-coding gene on chromosome 1 (158,610,704 to 158,686,715, reverse strand). Ensembl gene ENSG00000163554.
Subcellular location: Cytoplasm, cytoskeleton; Cytoplasm, cell cortex
Pathways (Reactome):
Developmental Biology: Interaction between L1 and Ankyrins; NCAM signaling for neurite out-growth
Signal Transduction: RAF/MAP kinase cascade
Vesicle-mediated transport: COPI-mediated anterograde transport
Gene Ontology:
Molecular function: protein binding; actin filament binding; structural constituent of cytoskeleton; calcium ion binding
Biological process: actin cytoskeleton organization; actin filament organization; regulation of cell shape
Cellular component: spectrin; spectrin-associated cytoskeleton; actin cytoskeleton; cell junction; cortical actin cytoskeleton; cytoplasmic side of plasma membrane; cytosol; plasma membrane; axon; cell cortex; cortical cytoskeleton; cuticular plate; cytoskeleton; membrane
Genetic constraint (gnomAD): Loss-of-function variants: 173 observed, 332.03 expected, observed/expected ratio (o/e) 0.52, 90% interval 0.46 to 0.59. The upper end of that interval is the gene's LOEUF score, 0.59, which puts it in group 2 of 6, group 1 being the genes least tolerant of losing a copy. Missense variants: 3,100 observed, 2,983.2 expected, observed/expected ratio (o/e) 1.04, 90% interval 1.01 to 1.07. Synonymous variants: 1,178 observed, 1,089.2 expected, observed/expected ratio (o/e) 1.08, 90% interval 1.03 to 1.13.
Homologues: Orthologues: chimpanzee SPTA1 (98% identical), macaque SPTA1 (94% identical), rabbit SPTA1 (82% identical), pig SPTA1 (81% identical), mouse Spta1 (80% identical), rat Spta1 (80% identical), dog SPTA1 (80% identical), guinea pig SPTA1 (77% identical). Paralogues in human: SPTAN1 (57% identical), SPTBN5 (23% identical), SPTBN1 (16% identical), SPTB (15% identical), SPTBN2 (15% identical), SPTBN4 (14% identical), MACF1 (13% identical), DST (13% identical), SYNE1 (12% identical), SYNE2 (10% identical), PLEC (10% identical), UTRN (9% identical), and 24 more.
Diseases named in the same sentence as SPTA1 in open-access papers:
SPTA1 is named in the same sentence as 73 diseases in open-access papers, as found by Europe PMC text mining. Sharing a sentence is not in itself a finding about the gene and the disease. The quoted sentences say what the papers report.
hereditary spherocytosis (22 papers, 2011 to 2025). Hereditary spherocytosis is a congenital hemolytic anemia with a wide clinical spectrum (from symptom-free carriers to severe hemolysis) characterized by anemia, variable jaundice, splenomegaly and cholelithiasis. "Severe recessive hereditary spherocytosis is primarily caused by biallelic mutations in the SPTA1 gene, with reduced SPTA1 mRNA expression in reticulocytes providing evidence of pathogenicity." (PMID 39439639, 2024). "We demonstrate the utility of this strategy in the induction of readthrough across the thalassemia-causing PTC in HBB mRNA and hereditary spherocytosis-causing PTC in SPTA1 mRNA." (PMID 38499809, 2024). "The SPTA1 variant is a common disease-causing variant and has already been reported in multiple patients with hereditary spherocytosis." (PMID 39439639, 2024). "Particularly interesting for us were five genes associated with clinical phenotypes of hereditary spherocytosis (SPTA1, SPTA, SLC4A1, ANK1, and EPB42)." (PMID 36979763, 2023). "SPTA1, which have been linked to hereditary elliptocytosis and hereditary spherocytosis, were reported as a possible tumor driver gene in prostate cancer and papillary thyroid carcinoma." (PMID 37223105, 2022). "SPTA1 mutation is associated with a variety of hereditary red blood cell disorders, such as hereditary elliptocytosis and hereditary spherocytosis." (PMID 34095982, 2021). "Null mutations in SPTA1 gene wereidentified in four families with hereditary spherocytosis (18, 24, 27, and 35)." (PMID 32266426, 2020). "Mutations in SPTA1 are responsible for hereditary spherocytosis, a monogenic disorder of MCHC, as well as for the normal MCHC level." (PMID 23935956, 2013). "Recessive spectrin-deficient hereditary spherocytosis (HS) can be linked to mutations in the SPTA1 gene, whether homozygous or compound heterozygous." (PMID 39439639, 2024). "Finally, spectrin alpha, erythrocytic 1 (Spta1) has been identified as one of the causative genes of Hereditary spherocytosis, and its role as a mediator transport functions." (PMID 36982506, 2023). "In total, 16 of the 23 patients with multi-locus diagnosis (70%) showed dual molecular diagnosis of hereditary stomatocytosis, most of which were affected by dehydrated hereditary stomatocytosis type 1 (DHS1), and hereditary spherocytosis mainly due to biallelic SPTA1 variants." (PMID 34201899, 2021). "The clinical features align closely with the manifestations of hypogammaglobulinemia and reduced B cell counts associated with BTK deficiency, as well as the severe chronic anemia observed in SPTA1-related hereditary spherocytosis." (PMID 39439639, 2024). "SPH1 (Spherocytosis, type 1), SPH2 (Spherocytosis, type 2), SPH3 (Spherocytosis, type 3), SPH4 (Spherocytosis, type 4), SPH5 (Spherocytosis, type 5) are caused by ANK1, SPTB, SPTA1, SLC4A1, and EPB42 gene mutations, respectively." (PMID 37795245, 2023). "Thirteen variants were identified in five hereditary spherocytosis-related genes (six in ANK1 [SPH1]; four in SPTB [SPH2]; and one in each of SPTA1 [SPH3], SLC4A1 [SPH4], and EPB42 [SPH5])." (PMID 35022413, 2022). "Mutations in SPTA1 were found in the monogenic disorder of MCHC, hereditary spherocytosis (HS, MIM ID #182900)." (PMID 23935956, 2013).
hereditary spherocytosis (continued). "Hereditary spherocytosis (HS) is an inherited disorder characterized by anemia, splenomegaly, and spherical-shaped erythrocytes, caused by mutations in erythrocyte membrane Protein Genes (ANK1, SPTB, SLC4A1, SPTA1, and EPB42)." (PMID 33014018, 2020). "Hereditary spherocytosis (HS) type III, an autosomal recessive disorder, affects the SPTA1 (alpha spectrin) gene on chromosome 1q23.1." (PMID 39439639, 2024). "However, genetic testing by NGS showed no mutations in ANK1, EPB42, SLC4A1, SPTA1, or SBTB genes in this and an additional two patients, thus ruling out hereditary spherocytosis in all studied cases." (PMID 35681698, 2022).
hereditary elliptocytosis (14 papers, 2012 to 2025). Hereditary elliptocytosis (HE) is a rare clinically and genetically heterogeneous disorder of the red cell membrane characterized by manifestations ranging from mild to severe transfusion-dependent hemolytic anemia but with the majority of patients being asymptomatic. "Our case contributes to the literature by identifying a homozygous missense mutation in exon 4 of the SPTA1 gene, further highlighting the genetic heterogeneity of hereditary elliptocytosis." (PMID 41020088, 2025). "This low-expression allele results in the expression of hereditary elliptocytosis (HE) when in trans with a pathogenic SPTA1 variant." (PMID 36979763, 2023). "The patient pEl presents a moderate to severe form of elliptocytosis, resulting from compound heterozygous mutations in the α-spectrin gene SPTA1." (PMID 32751168, 2020). "Forty‐one patients harbored the common SPTA1 mutation c.6531‐12C > T (α‐spectrinLELY), which is considered benign in itself but may cause overt HS, hereditary elliptocytosis or hereditary pyropoikilocytosis in trans to SPTA1 mutations." (PMID 35845192, 2021). "Here, we explored the molecular, biophysical, morphological, and functional consequences of α-spectrin mutations in a patient with hereditary elliptocytosis (pEl) almost exclusively expressing the Pro260 variant of SPTA1 and her mother (pElm), heterozygous for this mutation." (PMID 32751168, 2020). "αLELYin trans to an SPTA1 allele with a hereditary elliptocytosis (HE)-associated mutation modifies the phenotype from HE to hereditary pyropoikilocytosis." (PMID 31333484, 2019). "Of the 3 heterozygotes with a normal copy number of α globin genes one had co-inherited a mutation in the SPTA1 gene associated with HS, and another had co-inherited the SLC4A1 variant for south Asian Ovalocytosis." (PMID 31300739, 2019).
anemia (7 papers, 2019 to 2025). A reduction in the number of red blood cells, the amount of hemoglobin, and/or the volume of packed red blood cells. "αLEPRAin trans to a null SPTA1 allele (leading to a total α-spectrin production of about 8%) has been shown to cause severe autosomal recessive HS, with anemia and jaundice that resolve with splenectomy." (PMID 31333484, 2019). "Reports indicate that patients with mutations in exon 2 of the SPTA1 gene experience varying degrees of anemia, which may be due to incomplete exclusion of the mutated locus, where one allele may be silenced and not expressed." (PMID 39502561, 2024). "Patients carrying the low expression αLEPRA allele in trans to a null SPTA1 mutation were not all transfusion dependent and their anemia improved or resolved with partial or total splenectomy, respectively." (PMID 31333484, 2019).
glioblastoma (7 papers, 2019 to 2025). The most malignant astrocytic tumor (WHO grade IV). "In contrast, mutant SPTA1 is mutually exclusive to the core members of cell cycle pathways and is suggested to be associated with abnormal cell proliferation in glioblastoma development." (PMID 39061186, 2024). "While SPTA1 encodes a cytoskeletal protein, recent evidence suggests that its mutations may influence abnormal cell proliferation and apoptosis, as shown in glioblastoma studies, indicating a possible, yet incompletely understood, role in tumorigenesis." (PMID 41395625, 2025). "Mutations in SPTA1 was found to play a role in glioblastoma." (PMID 31568528, 2019). "On the contrary, the mutation of PTEN, EGFR, TTN, NF1, SPTA1 and RB1, which occurred frequently in glioblastoma, were more frequently in PVT1 higher group." (PMID 37202742, 2023). "Although not reported as driver gene in previous HCC studies, SPTA1 was reported as a possible tumor suppressor in Glioblastoma Multiforme36." (PMID 32873799, 2020).
lung adenocarcinoma (5 papers, 2016 to 2025). A carcinoma that arises from the lung and is characterized by the presence of malignant glandular epithelial cells. "Univariate Cox regression analysis suggested that the high expression levels of up-regulated DEGs including APOL1, ETFB, KLK8, PPP1R3G, PRL, and SPTA1 were significantly correlated with poorer overall survival (OS) in lung adenocarcinoma." (PMID 38183079, 2024). "Predictions of known cancer driver genes in new cancer types include SPTA1, CHD4 and ASXL1 in colorectal cancer, FOXO3, MUC16 and ZFPM1 in breast cancers and CNTNAP2, CTNND2 and TRRAP in lung adenocarcinoma." (PMID 38890488, 2024). "Of the 16 distinguishing proteins, 8 were significantly elevated in lung adenocarcinoma (COPG1, STOML2, HYOU1, PDIA4, EPRS, APEX1, LRPPRC and NANS) whereas 8 proteins were significantly decreased in lung adenocarcinoma (SPTB, SPTA1, ANK1, SLC4A1, HBG1 and HBG2)." (PMID 27799870, 2016).
colorectal cancer (4 papers, 2016 to 2024). A primary or metastatic malignant neoplasm that affects the colon or rectum. "Alterations in SPTA1 are associated with colorectal cancer and small-cell lung cancer." (PMID 31815141, 2019).
red blood cell disorders (4 papers, 2012 to 2023). "Mutations in SPTA1 result in a variety of hereditary red blood cell disorders." (PMID 37546388, 2023). "Rare mutations in many loci associated with HbA1c (SPTA1ANK1HK1TMPRSS6) are known to cause hereditary red blood cell disorders and common variants at several loci (SPTA1, HFE, ANK1HK1TMPRSS6) are associated with hematological traits like hemoglobin concentration and mean corpuscular volume." (PMID 22540250, 2012). "Consistent with the role of red blood cell disorders, we also found associations of RHAG (Rh Associated Glycoprotein) and SPTA1 with decreased levels of HbA1c." (PMID 36088354, 2022).
Pyropoikilocytosis (3 papers, 2020 to 2021). A form of severe hemolytic anemia characterized by erythrocyte morphology reminiscent of that seen in patients after a thermal burn. "Mutations in SPTA1 can lead to a variety of hereditary red blood cell disorders, including elliptocytosis type 2, pyropoikilocytosis, and spherocytic hemolytic anemia." (PMID 33148303, 2020). "The severe recessive variant is hereditary pyropoikilocytosis, in which the significant membrane fragmentation and reduced surface area is mostly caused by a pathogenic mutation in SPTA1 gene inherited in trans to the hypomorphic variant αLELY (Low Expression LYon)." (PMID 32655575, 2020).
thalassemia (3 papers, 2022 to 2024). An inherited blood disorder characterized by a decreased synthesis of one of the polypeptide chains that form hemoglobin. "In our study, we found overexpression of the genes SLC4A1, ANK1, EPB41, EPB42, SPTA1, SPTB, and STOM, all of which are involved in maintaining erythrocyte structure and function, in patients with thalassemia and SCD." (PMID 39519257, 2024).
gastric cancer (2 papers, 2022 to 2025). A primary or metastatic malignant neoplasm involving the stomach.
haemoglobinopathies (2 papers, 2022 to 2024). "Our meta-analysis identified several genes associated with Mendelian haemoglobinopathies as sites of ancestral heterogeneity in the genetic architecture of HbA1c (e.g. spectrin [SPTA1], ankyrin [ANK], PIEZO1)." (PMID 39414775, 2024).
malaria (2 papers, 2017 to 2018). Malaria is a serious and sometimes fatal disease caused by a parasite that commonly infects a certain type of mosquito which feeds on humans. "Overall, these observations suggest that malaria parasites contributed to the shaping of SPTA1 genetic diversity in primates." (PMID 30279439, 2018). "These deformations are more common in individuals of African descent, leading to the hypothesis that SPTA1 is involved in malaria resistance in humans." (PMID 28957326, 2017). "Together, branch- and domain-specific patterns of adaptation in SPTA1 support malaria as an important, but by no means unique, influence on the evolution of mammalian red blood cells." (PMID 28957326, 2017). "Notably, we do not claim that all adaptation in SPTA1 is due to pressure from malaria." (PMID 28957326, 2017).
Sepsis (2 papers, 2021 to 2022). Sepsis is defined as life-threatening organ dysfunction caused by a dysregulated host response to infection. "Five genes (NKG7, SPTA1, FGL2, RGS2, and IFI27) have been proved to be potential biomarkers for sepsis-induced ARDS and exert crucial roles in the occurrence and development of sepsis." (PMID 36299685, 2022). "In summary, our study identified five key genes including NKG7, SPTA1, FGL2, RGS2, and IFI27, which were closely related to the sepsis-induced ARDS development." (PMID 34393665, 2021). "Moreover, five genes including NKG7, SPTA1, FGL2, RGS2, and IFI27 exhibited notable difference between the sepsis-induced ARDS group and the control group with sepsis alone in two datasets, suggesting that these five genes might be key genes that led to sepsis patients complicated with ARDS." (PMID 34393665, 2021). "Furthermore, five genes including NKG7, SPTA1, FGL2, RGS2 and IFI27 exhibited significant differences between the sepsis-induced ARDS samples and the samples with sepsis alone in two datasets, suggesting that these five genes might be key genes that led to sepsis patients complicated with ARDS." (PMID 34393665, 2021).
Spherocytosis, type 3 (2 papers, 2022 to 2023). "Moreover, among the African ARSA SNPs, there were three SNPs corresponding to mutations in SPTA1 associated with spherocytosis type 3 (rs16840450, rs35121052, and rs7547313), which leads to lower malaria parasitemia." (PMID 36011383, 2022).
arteriosclerosis (1 paper, 2023). A vascular disorder characterized by thickening and hardening of the walls of the arteries. "GeneChip analysis revealed increased six key genes during the process of arteriosclerosis including Apol11b, Camp, Chil3, S100a8, S100a9, and Spta1." (PMID 36982506, 2023).
cataract (1 paper, 2024). Partial or complete opacity of the crystalline lens of one or both eyes that decreases visual acuity and eventually results in blindness. "Moreover, the downregulation of SPTA1 (spectrin alpha, erythrocytic 1) and SERPINA1 (serpin family A member 1) was also confirmed in glaucoma patients in comparison to ICL and/or cataracts patients, as previously observed by mass spectrometry." (PMID 39000104, 2024).
chronic kidney disease (1 paper, 2024). Impairment of the renal function secondary to chronic kidney damage persisting for three or more months. "The proteomic analysis of an advanced chronic kidney disease (CKD) cohort identified that proteins SPTA1, MYL6 and C6, when used alongside the 4-variable UK-KFRE, achieve an improved performance when predicting a 5-year risk of ESRD." (PMID 38762513, 2024).
COVID-19 (1 paper, 2022). A disease caused by infection with severe acute respiratory syndrome coronavirus 2. "In SARS-CoV-2 infected individuals increased levels and oxidation of SPTA1 peptides are noted reflecting structural aberration of RBCs, which may potentially contribute to the severity of hypoxemia, thromboembolism, and coagulation defects noted in the manifestation of COVID-19." (PMID 36143338, 2022).
hepatocellular carcinoma (1 paper, 2021). A malignant tumor that arises from hepatocytes. "In addition, in a recent study on Mongolians with hepatocellular carcinoma, SPTA1 was reported as a potential driver gene." (PMID 34095982, 2021).
Hypertension (1 paper, 2023). The presence of chronic increased pressure in the systemic arterial system. "Conversely, the upregulation of PPN and downregulation of SPTB1 and SPTA1 were unique to hypertension." (PMID 36902363, 2023).